LIMK1 (LIM domain kinase 1)
Diseases named in the same sentence as LIMK1 in open-access papers (continued):
Sharing a sentence is not in itself a finding about the gene and the disease.
tumor (continued). "The correlative expression profile of LIMK1 and MT1-MMP was also detected in clinical samples pathological reports of which showed higher tumor grades." (PMID 21219645, 2011). "Experimental data demonstrate that LIMK1 and CDK5 synergistically facilitate cancer metastasis through a mechanism dependent on phosphorylation and co-targeting LIMK1 and CDK5 significantly suppresses tumor metastasis." (PMID 41614944, 2026). "Second, our current work demonstrates the essential role of LIMK1 and CDK5 in tumor metastasis." (PMID 40476449, 2025). "Furthermore, the feasibility of combined targeting of LIMK1 and CDK5 for targeted therapy of tumor metastasis was investigated in a preclinical setting." (PMID 40476449, 2025). "Moreover, the tumours derived from LIMK1/LIMK2-knockdowned TICs were significantly smaller, as they grew slower compared to the tumours derived from the control TICs." (PMID 36899941, 2023). "To date, inhibitors targeting LIMK1 and LIMK2 have shown potent tumor-suppressive effects." (PMID 37894409, 2023). "Recent studies have shown that Ce6-PDT inhibits tumor cell migration by destroying the structure of actin cytoskeleton and reducing lamellipodium formation, which is closely related to the downregulation of Rac1/PAK1/LIMK1/cofilin." (PMID 37049739, 2023). "At the same time, western blot analysis confirmed that knockdown of circ-LIMK1 could decrease the protein level of HMGA1 in tumor tissues and the tumor tissues after treatment with DDP." (PMID 36304135, 2022). "In the beginning, the results of RT-qPCR analysis proved that circ-LIMK1 was raised in tumor tissues (n = 56/group) than that in normal tissues." (PMID 36304135, 2022). "The precise balance between expression and subcellular localization of CFL-1, LIMK1, and SSH1 is pivotal for small changes in the dynamics of the actin cytoskeleton, and may augment features of tumor aggressiveness, including tumor dissemination." (PMID 33482809, 2021). "Reinforcing this suggestion, it was reported that LIMK1 is crucial for invasiveness and metastatic activity, and regulating the phosphorylation of CFL-1 during mitosis contributes to appropriate cytokinesis, proliferation, and extension of the tumor." (PMID 33482809, 2021). "LIMK1 activation can promote the phosphorylation of ADF/cofilin (downstream signaling molecules of LIMK1), result in reducing the depolymerization of ADF/cofilin and regulating actin cytoskeletal reorganization, which further promote tumor cell filopodia formation and metastasis." (PMID 28358024, 2017). "Moreover, the effect of LIMK1 knockdown and overexpression on the DADS-induced inhibition of tumor growth were confirmed in in vivo experiments." (PMID 26871290, 2016). "LIMK1, HOXC6 and PLXNA1 represent potential novel candidate genes for driving tumor growth of ERMS." (PMID 24009521, 2013). "In addition, the LIMK2 inhibitor T56-LIMKi inhibited the growth of subcutaneous tumor models of PAAD in mice by specifically inhibiting LIMK2 without cross-reacting with LIMK1." (PMID 37894409, 2023). "In brief, knockdown of circ-LIMK1 could weaken the tumor DDP resistance, DDP did not affect the expression of circ-LIMK1." (PMID 36304135, 2022). "Therefore, an analysis of the profile of gene and protein expression of CFL-1 and its regulators, LIMK1/SSH1, may provide important insights into the local invasion processes of primary tumor cells and could help in disease stratification in routine pathology." (PMID 33482809, 2021). "However, whether specific miRNAs regulate the expression of LIMK1 and thereby modulate TNBC cell motility and tumor progression is not well understood." (PMID 29156719, 2017). "Likewise, we observed a correlation between negative pCFL and negative LIMK1 expression in the tumor centre, (p=0.0001)." (PMID 25237832, 2014).
tumor (continued). "Such opposite findings suggest that targets of LIMK1 and LIMK2, which include ADF as well as cofilin, bring about different effects, which could be dependent on relative amounts of ADF or cofilin that are expressed in the different tumor cell types." (PMID 24093776, 2013). "Thus, some researchers have suggested that LIMK1 may play a role in regulating tumor progression via other mechanisms, independent of cofilin." (PMID 28025492, 2016). "Some double-negative feedback loops, including miR-143 (LIMK1, SOX2) and miR-145 (ADAM17, NEDD9, SOX2), also result in miR-143 and miR-145 downregulation in tumor cells." (PMID 35205713, 2022). "Last but not the least, IHC assay provided that knockdown of circ-LIMK1 or DDP treatment could reduce the expression of Ki67 and HMGA1 in tumor tissues, and Ki67 and HMGA1 were lowest after knockdown of circ-LIMK1 and treatment with DDP." (PMID 36304135, 2022).
cancer (91 papers, 2007 to 2026). A tumor composed of atypical neoplastic, often pleomorphic cells that invade other tissues. "In colon cancer cell lines, LIM kinase 1 (LIMK1) has emergedasa potential therapeutic target since its overexpression in this typeof cancer is associated with increased migration and invasion of coloncancer cells." (PMID 36858050, 2023). "Recent studies have characterized LIMK1 as an important biomarker for poor prognosis and associated upregulated mRNA expression of LIMK1 with poor overall survival in many cancers." (PMID 34149814, 2021). "Several other independent studies have also reported that LIMK1 expression is closely associated with many kinds of cancers." (PMID 30873211, 2019). "Furthermore, it is reported that LIMK1 is upregulated in various cancers and associates with an unfavorable prognosis." (PMID 34149814, 2021). "Studies have indicated that overexpressed LIMK1 can boost the invasion, metastatic ability, and progression of cancer cells." (PMID 41246964, 2025). "The in vitro and in vivo experiments demonstrated that LIMK1 cooperates with Cyclin‐dependent kinase 5 (CDK5) to promote cancer metastasis in a phosphorylation‐dependent manner." (PMID 40476449, 2025). "Studies on prostate cancer cells proved that targeting the RAC2/PAK4/LIMK1/cofilin pathway impeded cancer progression and reinstated arsenic-induced cancer cell apoptosis." (PMID 40072059, 2025). "This work highlights LIMK1 as a novel regulatory and targetable kinase of β‐catenin, informing the treatment of advanced cancer." (PMID 40476449, 2025). "The results showed that the relative protein expression of LIMK1 in cancer tissues (1.11±0.19) was significantly higher than that in pericancerous tissues (0.27±0.14)." (PMID 38975937, 2024). "Immunohistochemical analysis of cancer and paracancer tissues revealed that LIMK1 was highly expressed in OS tissues." (PMID 37894409, 2023). "MiR-143, miR-23a, and nuclear clusterin exert cancer-suppressive effects by blocking the activation of LIMK1/Cofilin." (PMID 37894409, 2023). "In cancer studies, miR-520a has been associated with suppression of oncogenic signaling pathways including CDK4, SUV39H1, LIMK1, GOT-2, AKT1/mTOR, and PI3K/AKT31–37." (PMID 35149732, 2022). "Here, in this study, based on pan-cancer analysis, our results are consistent with those reports that LIMK1 mRNA is abnormally expressed in various cancers." (PMID 34149814, 2021). "To evaluate the mRNA expression pattern of LIMK1 across different cancer types, we excluded from the analysis the datasets from 15 cancer types that contained less than five samples in the normal group." (PMID 34149814, 2021). "Although LIMK1 promotes cancer cell metastasis, it also plays an important role in the nervous system." (PMID 33883692, 2021). "Other studies have shown LIMK1 acts as a direct target of miRNA-27-3p and miRNA-128-3p, both miRNA-27-3p and miRNA-128-3p can suppress cancer cell proliferation, migration, and invasion." (PMID 34149814, 2021). "LIMK1 overexpression was occurred in various human cancer types such as colorectal cancer and breast cancer." (PMID 33344441, 2020). "On the other hand, to clarify the underlying molecular mechanism of inhibitory effect on invasion of GL-1196, we investigated its impact on the PAK4/LIMK1/cofilin signaling pathway that was reported to be essential for cancer cell migration and invasion." (PMID 27077843, 2016). "Inactivating cofilin/ADF by LIMK1 via phosphorylation results in the formation of membrane protrusions, which facilitates cancer cell migration and invasion." (PMID 26871290, 2016). "In fact, a study demonstrated that both up-regulated cofilin and LIMK1 expressions were identified in invasive cancer cells isolated from the primary mammary tumours." (PMID 26592552, 2015).
cancer (continued). "The two novel LIMK inhibitors described in the present study, CRT0105446 and CRT0105950, are potent inhibitors of LIMK1 and LIMK2 that will enable further development of LIMK-targeted cancer therapy." (PMID 26540348, 2015). "A review summarized that increased cofilin, decreased phosphorylated cofilin and increased LIMK1 expressions were usually found in highly invasive cancer cells." (PMID 26592552, 2015). "It has recently emerged that LIMK1 and LIMK2 also influence microtubule dynamics and have important functions in mitosis, which is consistent with LIMK inhibitors being potential cancer therapeutics." (PMID 26540348, 2015). "The reductions in metastases and in cancer cell-induced angiogenesis were similar for each of the LIMK1 and the LIMK2 single knockdowns." (PMID 25593987, 2014). "LIMK1/2 are dual-specificity kinases that function in organization of the actin and microtubule cytoskeletons, cell-motility processes including cancer metastasis, and cell cycle progression." (PMID 22883572, 2012). "While it has been presumed that the mechanism by which LIMK1 promotes cancer progression is via its cytoplasmic effects, the role of nuclear vs cytoplasmic LIMK1 in the tumorigenic process has not been examined." (PMID 21682918, 2011). "Despite these advances in our understanding of LIMK1 functions, several key questions remain regarding the ability of LIMK1 to promote cancer progression." (PMID 21682918, 2011). "An increase in ROCK levels has been detected in several human cancers and levels of LIMK-1 increase in invasive and metastatic breast and prostate cell lines." (PMID 18852895, 2008). "LIMK1 is related to cancer cell proliferation, migration, invasion, and metastasis." (PMID 41246964, 2025). "Key genes (ACTIN1, LIMK1, CORO1C, INF2, SH3D21, CFL1, FSCN1, MYO1B) implicated in actin cytoskeleton organization were identified, suggesting their role in oral potentially malignant disorders and cancer progression." (PMID 40818124, 2025). "The biological roles and regulatory mechanisms of LIMK1 in the Wnt/β‐catenin signaling pathway and cancer metastasis remain largely unknown to date." (PMID 40476449, 2025). "LIMK1 is overexpressed and essential in various types of cancer." (PMID 41246964, 2025). "In its inactivated state, cofilin is phosphorylated at serine 3 by LIMK1 or LIMK2, and dephosphorylation caused by inhibiting LIMK1/2 leads to the activation of cofilin, and consequently to actin reorganization and mitochondrial apoptosis in cancer cells." (PMID 36431240, 2022). "Both LIMK1 and LIMK2 belong to the LIMK family; despite their structural similarities, the LIMK1/LIMK2 may have different roles in cancer development and progression." (PMID 35273591, 2022). "All these results suggest that LIMK1 could be regarded as a promising biomarker or emerging target for cancer therapy." (PMID 34149814, 2021). "Compared with normal tissues, LIMK1 was significantly upregulated in 16 of all 18 cancer types." (PMID 34149814, 2021). "LIMK1 suppresses actin-severing activity and impacts actin cytoskeletal organization, including F-actin fiber arrangement and invadopodium actin dynamics by phosphorylating cofilin, which affects the process of invasion in different types of cancer." (PMID 34079084, 2021). "Hence, the possible adverse effects of LIMK1 inhibition on the nervous system should be taken into consideration prior to its application to cancer treatment." (PMID 33883692, 2021). "However, beyond the changes of cancer cells themselves, the degradation of ECM is essential for cancer invasion, and LIMK1 has also been reported involved in this process." (PMID 34079084, 2021). "Inhibition of LIMK1 also shows beneficial effects in cancer." (PMID 34966720, 2021). "LIM kinase 1 (LIMK1) is a serine/threonine kinase, which is highly upregulated in human cancers." (PMID 33344441, 2020). "LIMK1 and its upstream signaling factors could work as valuable targets for anti-cancer metastasis therapies." (PMID 31541994, 2019).
cancer (continued). "Higher levels of LIMK1 are reported during the progression of many cancers." (PMID 30873211, 2019). "Cancer tumorigenesis and metastasis are affected when activated LIMK1 phosphorylates CFL1." (PMID 30873211, 2019). "Multiple studies have confirmed that miRNAs could regulate the expression of LIMK1 and affect its biological function in different cancer types." (PMID 30873211, 2019). "Although we observe multi-polar spindles in LIMK1-knockdown cells, these extra spindle poles may eventually coalescence/cluster to become bipolar spindles before anaphase onset especially in cancer cells." (PMID 29925632, 2018). "LIMK1 has been shown to be overexpressed or overactive in a variety of malignant tumors." (PMID 28358024, 2017). "LIMK1 and its upstream signaling factors could be valuable targets for anti-cancer metastasis therapies." (PMID 26871290, 2016). "This coordinated overexpression of cofilin and LIMK1 might increase the rate of cofilin acticity in invasive cancer cells, leading to actin polymerization transients as well as facilitating cancer cell invasion." (PMID 26592552, 2015). "Involvement of LIMK1/2 in cancer has become a major focus of interest in the last few years." (PMID 25593987, 2014). "Nischarin was shown to interact specifically with the phosphorylated form of LIMK1 on Thr508 via co-immunoprecipitation experiments, leading to its dephosphorylation and inhibition, and resulting in lower amounts of phospho-cofilin and impaired cancer cell invasion." (PMID 36899941, 2023). "LIMK1 is activated from the upstream kinase such as Rho‐associated coiled‐coil‐containing protein kinase (ROCK) and transfer the signal to downstream effecter, cofilin by phosphorylation thereby promotes cancer cell growth through regulation of actin/filament dynamics." (PMID 33982869, 2021). "However, in contrast, overexpressed LIMK1 was also found to reduce cancer cell motility." (PMID 26592552, 2015). "While the genes for LIMK1/2 do not appear to be the target of mutations in human cancers, the subversion of their expression may be important in the process of cancer cell migration and metastasis." (PMID 25237832, 2014). "Another intracellular biomarker involved in cancer cell migration, the metastatic process, and androgenic signaling is LIM domain kinase 1 (LIMK1)." (PMID 37371647, 2023). "Knockdown of circ-LIMK1 reduced DDP resistance, impaired cancer cell growth, migration, invasion, and angiogenesis." (PMID 36304135, 2022). "LIM domain kinase (LIMK) is a class of serine/threonine protein kinases; previous studies indicated that LIMK1 was highly expressed in numerous malignant tumors and correlated with patients’ poor prognoses." (PMID 35273591, 2022). "Down-regulated miR-128-3p and up-regulated LIMK1 can be induced by FOXD3-AS1, which contribute to cancer progression." (PMID 34395290, 2021). "LIMK1 is a crucial component of Rac1/PAK1/LIMK1/cofilin signaling pathway, which is involved in several cancers." (PMID 34149814, 2021). "Based on these results, it can be stated that further research is required to analyze different aspects of LIMK1 and LIMK2 in various types of cancer." (PMID 34843456, 2021). "The balance of kinases (LIMK1) and phosphatases (SSH1) can change the activation of cofilin, and LIMK1 and SSH1 have been extensively studied as regulators in cofilin-mediated pathways in cell motility and cancer metastasis." (PMID 33614640, 2021). "Cofilin-1 (CFL-1) and its modulators, LIMK1/SSH1, play key roles in mediating the invasiveness by driving actin cytoskeleton reorganization in various cancer types." (PMID 33482809, 2021). "LIMK contains two distinct protein kinases (LIMK1, LIMK2) and both of them had been verified to be involved in cancer progression and metastasis." (PMID 32205841, 2020).
cancer (continued). "Several reports have shown that modulating LIMK1 expression by antisense, by overexpression of LIMK1 by a dominant negative form, or by knockdown of LIMK2 by ribozyme-mediated knockdown will inhibit cancer motility, invasion, and metastasis." (PMID 25237832, 2014). "Similar to fascin-1, LIMK1 and LIMK2 contribute functionally to cancer cell invasion and metastasis, and are therefore of interest as therapeutic targets." (PMID 22883572, 2012). "Inspiring, we further extended the regulatory network of β‐catenin function and elucidated the intrinsic mechanism by which LIMK1 and CDK5 perform similar functions, introducing novel insights for targeted therapy of cancer treatment using CDK5 in combination with another agent." (PMID 40476449, 2025). "Mechanistically, LIMK1 and CDK5 synergistically phosphorylate β‐catenin at S191, enhancing its phosphorylation and interaction with Nucleoporin 93, resulting in β‐catenin nuclear translocation and activation of key pathways in cancer metastasis." (PMID 40476449, 2025). "Results revealed that the upregulation of LIMK1 or CDK5 shared similar activated/inhibited signaling pathways including focal adhesion, ECM‐receptor interaction, cell cycle, and some critical signaling pathways in cancer." (PMID 40476449, 2025). "While additional miRNAs have been shown to target LIMK1 in cancer cells, we are not aware of miRNAs that regulate LIMK1 or APT1 in neurons, apart from miR‐134 and mir‐138, respectively." (PMID 29712715, 2018). "LIM kinases (LIMK), a family of two highly related members, LIMK1 and LIMK2, which control both actin and microtubule dynamics and are overexpressed in many invasive cancers, are an attractive target." (PMID 30550596, 2018). "The results suggested that DADS could downregulate the expression of LIMK1 to impair the expression of vimentin, CD34, and Ki-67 and increase the expression of E-cadherin, thereby inhibiting cancer growth, invasion, and metastasis." (PMID 28358024, 2017). "The results suggested that DADS downregulated LIMK1 expression to decrease the expression of vimentin, CD34, and Ki-67; increase E-cadherin expression; and impede cancer cell proliferation, angiogenesis, and EMT alteration, thereby inhibiting invasion and metastasis." (PMID 28358024, 2017). "Our findings may highlight the strategy of targeting actin-binding proteins, such as cofilin or cofilin regulators such as LIMK1/2, rather than actin itself for cancer therapy." (PMID 25003327, 2014). "Again, as in the normal tissues, the cancer tissues were generally not homogeneous for a given phenotype of LIMK1 localization; however, the tissues could easily be labeled as predominantly cytoplasmic, or predominantly cytoplasmic plus nuclear in nature." (PMID 21682918, 2011).